MMP15 (matrix metallopeptidase 15)
Description:
Endopeptidase that degrades various components of the extracellular matrix. May activate progelatinase A.
Synonyms: MMP-15; MTMMP2; MT2-MMP; MT2MMP; SMCP-2
Tractability: Small molecule: a high-quality ligand is known; it belongs to a druggable protein family. Antibody: UniProt places it where antibodies can reach, with high confidence; its Gene Ontology location is reachable by antibodies, with high confidence; UniProt predicts a signal peptide or a membrane-spanning region; the Human Protein Atlas places it where antibodies can reach. PROTAC: ubiquitination databases record sites on it; a small molecule that binds it is known.
Target class: Metallo protease; Metallo protease M10A subfamily; Metallo protease MAM clan; Protease; Enzyme
Gene: Protein-coding gene on chromosome 16 (58,025,606 to 58,046,901, forward strand). Ensembl gene ENSG00000102996.
Subcellular location: Membrane
Subcellular location (Human Protein Atlas): Cytosol; Plasma membrane; Nucleoplasm
Pathways (Reactome):
Extracellular matrix organization: Activation of Matrix Metalloproteinases; Collagen degradation; Degradation of the extracellular matrix
Gene Ontology:
Molecular function: protein binding; enzyme activator activity; metalloaminopeptidase activity; metalloendopeptidase activity; zinc ion binding; metallopeptidase activity
Biological process: endodermal cell differentiation; collagen catabolic process; extracellular matrix disassembly; extracellular matrix organization; protein modification process; proteolysis; response to estradiol
Cellular component: plasma membrane; extracellular matrix; membrane
Genetic constraint (gnomAD): Loss-of-function variants: 36 observed, 62.28 expected, observed/expected ratio (o/e) 0.58, 90% interval 0.44 to 0.76. The upper end of that interval is the gene's LOEUF score, 0.76, which puts it in group 3 of 6, group 1 being the genes least tolerant of losing a copy. Missense variants: 870 observed, 948.96 expected, observed/expected ratio (o/e) 0.92, 90% interval 0.87 to 0.97. Synonymous variants: 428 observed, 386.78 expected, observed/expected ratio (o/e) 1.11, 90% interval 1.02 to 1.2.
Homologues: Orthologues: chimpanzee MMP15 (99% identical), pig MMP15 (94% identical), dog MMP15 (94% identical), guinea pig MMP15 (92% identical), macaque MMP15 (92% identical), rabbit MMP15 (89% identical), mouse Mmp15 (87% identical), rat Mmp15 (87% identical), tropical clawed frog mmp15 (66% identical), zebrafish mmp15b (64% identical), zebrafish mmp15a (52% identical), Caenorhabditis elegans zmp-3 (24% identical), and 4 more. Paralogues in human: MMP14 (50% identical), MMP16 (49% identical), MMP24 (49% identical), MMP25 (30% identical), MMP17 (29% identical), MMP3 (28% identical), MMP12 (27% identical), MMP1 (27% identical), MMP8 (27% identical), MMP10 (27% identical), MMP2 (27% identical), MMP27 (26% identical), and 11 more.
Diseases named in the same sentence as MMP15 in open-access papers:
MMP15 is named in the same sentence as 76 diseases in open-access papers, as found by Europe PMC text mining. Sharing a sentence is not in itself a finding about the gene and the disease. The quoted sentences say what the papers report.
breast carcinoma (11 papers, 2009 to 2023). "Knockdown of MMP15 yielded decreased invasion, demonstrating the implication of MMP15 and obesity status in the invasive capacity of ASCs, which have been associated with increased breast cancer tumorigenesis and metastasis." (PMID 37445827, 2023). "MMP15 may increase the level of integrin 6 (ITGB6) by mediating Rho-Rac pathway, leading to breast cancer cell metastasis, which is consistent with the poor prognosis of breast cancer patients caused by high-level expression of MMP15 in this study." (PMID 35069702, 2021). "Other studies are still required to understand the molecular mechanisms behind MMP15-mediated invasion of ASCs in breast cancer." (PMID 37445827, 2023). "MMP15 mediates LncRNA MAFG-AS1-promoted the aggressiveness of breast carcinoma, and the migration and invasion of non-small-cell carcinoma (NSCLC)." (PMID 32887509, 2020). "Furthermore, the lncRNA MAFG-AS1 was upregulated in breast cancer and facilitated breast carcinoma progression by regulating MMP15 expression." (PMID 35992831, 2022). "MMP15 regulates LncRNA MAFG-AS1-promoted the aggressiveness of breast carcinoma." (PMID 32887509, 2020). "Silencing KDM2A using small interfering RNAs increased the invasion and migration of breast cancer cells by suppressing a subset of matrix metalloproteinases, such as MMP-2, MMP-9, MMP-4 and MMP-15." (PMID 26430963, 2015). "This study identifies MMP15 as a protease that may allow ASCs egress through ECM barriers and invasion of surrounding tissue in the context of breast cancer." (PMID 37445827, 2023). "Taken together, these results indicate that the E2F1-mediated expression of MMP2, MMP9, MMP14, and MMP15 might be repressed by KDM2A, eventually hindering the migration and invasion of breast cancer cells." (PMID 25029110, 2014). "The results showed that MMP9, MMP12, MMP15, and MMP27 groups were all highly variable (p < 0.01), whereas the other groups were not markedly different, indicating that these genes may play important roles in the occurrence and development of breast cancer." (PMID 35069702, 2021).
bladder cancer (6 papers, 2020 to 2025). "MMP15 is also associated with malignancy, aggressiveness, and survival prognosis in human urinary bladder cancer by activating other MMPs." (PMID 34587931, 2021). "The underlying mechanism how LINC00482, FOXA1 and MMP15 function in bladder cancer was further investigated to study the underlying mechanisms, bladder cancer cells were transfected with sh-MMP15, sh-NC, oe-LINC00482 + oe-FOXA1 + sh-MMP15, or oe-LINC00482 + oe-FOXA1 + sh-NC." (PMID 33323547, 2020). "The total content of MMP15 in the tissue of low-grade bladder cancer is 36.638 ± 4.895 μg/mg protein, while in the tissue of high-grade bladder cancer it is lower, at 22.974 ± 3.042 μg/mg protein." (PMID 41228251, 2025). "MMP14 and MMP15, both belonging to the group of membrane-type proteinases, were compared as bladder cancer biomarkers." (PMID 41228251, 2025). "The level of MMP14 grows significantly with the grade of bladder cancer, while changes in MMP15 content in bladder cancer tissue, depending on the grade of the disease, are inconsistent." (PMID 41228251, 2025). "MMP15 is highly expressed in bladder cancer tissue and contributes to inflammation and angiogenesis in bladder cancer." (PMID 41228251, 2025). "MMP15 is highly expressed in bladder cancer and contributes to inflammation and angiogenesis in cancer cells." (PMID 34587931, 2021). "Comparison of investigated enzymes’ activity and the inhibitor content suggested it opposite effects, higher suppression of MMP-14 than MMP-15 activity in low-grade bladder cancer and reverse TIMP-1 action in high-grade cancer." (PMID 32049862, 2020). "The data from the current study showed that MMP15 expression was significantly increased in bladder cancer tissues and cells." (PMID 33323547, 2020). "Comparison of investigated enzymes’ activity and the inhibitor content suggests it opposite effects, higher suppression of MMP-14 than MMP-15 activity in low-grade bladder cancer and reverse TIMP-1 action in high-grade cancer." (PMID 32049862, 2020). "The initial step was to detect the expressions of LINC00482 and MMP15 in bladder cancer cells and tissue." (PMID 33323547, 2020). "The expression of MMP15 in bladder cancer tissues and cells was detected by immunohistochemistry and the RT-qPCR analysis." (PMID 33323547, 2020). "According to the results from the RT-qPCR, LINC00482 and MMP15 were both highly expressed in bladder cancer cells and tissue." (PMID 33323547, 2020). "The specific activity of investigated metalloproteinases was considerably higher for MMP-14 than for MMP-15, especially in the high-grade urinary bladder cancer." (PMID 32049862, 2020). "They showed that MMP15 expression was significantly higher in bladder cancer tissues and cells (all p < 0.05)." (PMID 33323547, 2020). "The actual activity of MMP-15 found in low-grade urinary bladder cancer was more than 3 times higher." (PMID 32049862, 2020). "The low-grade urinary bladder cancer was distinguished by a significant increase in specific activity of MMP-15." (PMID 32049862, 2020). "In the current study, our findings suggested that silencing LINC00482 could potentially inhibit the proliferation, migration, invasion of bladder cancer cells through the up-regulation of MMP15 via recruiting FOXA1." (PMID 33323547, 2020). "Furthermore, LINC00482 was indicated to positively correlate with MMP15 expression in bladder cancer tissues (p < 0.05), when the correlation analysis between LINC00482 and MMP15 expression was carried out on the 84 paired bladder cancer tissues." (PMID 33323547, 2020). "MMP-14 dominates over MMP-15, particularly in high-grade urinary bladder cancer." (PMID 32049862, 2020). "Moreover, we found that silencing LINC00482 inhibited inflammation and angiogenesis in bladder cancer through the down-regulation of MMP-15 by targeting FOXA1, along with decreased levels of TNF-α, IL-1β, and IL-6 as well as the expression of VEGF and NF-κB." (PMID 33323547, 2020).
bladder cancer (continued). "Several other MMPs are also considered as bladder cancer biomarkers: MMP1, MMP3, MMP7, MMP14, and MMP15." (PMID 41228251, 2025). "LINC00482 promotes MMP15 expression by recruiting FOXA1, leading to the inhibition of inflammation and angiogenesis in bladder cancer, consistent with our results." (PMID 36879212, 2023). "The present study demonstrated that LINC00482 induced the expression of MMP15 by interacting with FOXA1, thereby contributing to the inflammation and angiogenesis in bladder cancer." (PMID 33323547, 2020). "Based on our in vitro and in vivo results, we conclude that silencing LINC00482 could down-regulate the expression of MMP15 via targeting FOXA1, which results in the inhibition of proliferation, migration, invasion of bladder cancer." (PMID 33323547, 2020). "Among the lncRNAs used to establish the signature, LINC00482 is overexpressed in bladder cancer tissues and cells, and silencing LINC00482 may inhibit the proliferation, migration and invasion of bladder cancer by repressing the expression of MMP15 by targeting FOXA144." (PMID 35778526, 2022).
lung carcinoma (6 papers, 2016 to 2025). "Actually, we demonstrated that the TCF-4/MMP-15 pathway was causally linked to the invasion and metastasis of lung cancer cells." (PMID 27046058, 2016). "Both TCF-4 and MMP-15 are closely linked to the development of lung cancer, while the regulatory role of TCF-4 in MMP-15 expression is still obscure." (PMID 27046058, 2016). "In lung cancer, low-dose butyrate enhances tumour growth and metastasis through extracellular matrix remodelling, upregulation of MMP15, and HDAC2-dependent activation of the oncogenic lncRNA H19, which also promotes M2 macrophage polarization." (PMID 40925904, 2025). "In lung cancer, miR-148a targets MMP15 and ROCK1, resulting in reduced tumorigenesis and increased TRAIL dependent apoptosis." (PMID 28915601, 2017). "Here in this study, we identified MMP-15 as a target gene of TCF-4 in lung cancer cells, providing a mechanism linking Wnt signaling and TCF-4 to the metastasis and progression of lung cancer." (PMID 27046058, 2016). "In conclusion, we are the first to identify TCF-4 as a co-activator of NF-κB p65 to promote MMP-15 transcription and potentiate the migration activity of the lung cancer cells." (PMID 27046058, 2016). "In the present study, we identified that at least MMP-15 was rather important in TCF-4-midiated metastasis of lung cancer." (PMID 27046058, 2016). "In conclusion, we are the first to identify TCF-4 as a co-activator of NF-κB p65 to promote MMP-15 transcription and potentiate the migration activity of lung cancer cells." (PMID 27046058, 2016). "To observe the association between TCF-4 and MMP-15 in lung cancer, we firstly demonstrated that both TCF-4 and MMP-15 mRNA levels were notably elevated in lung cancer cells (H460, A549 and LLC) versus the normal epithelial cells SAEC." (PMID 27046058, 2016). "Moreover, we previously reported that MMP15, under the control of the transcriptional co-factor LPP, digests N-cadherin in lung cancer cells, and that loss of LPP function caused abnormal stabilization of N-cadherin." (PMID 35174090, 2022). "In this study, we are to observe whether and how TCF-4 would regulate MMP-15 expression and their roles in the progression of lung cancer." (PMID 27046058, 2016). "Blockage of the TCF-4/MMP-15 pathway might represent an effective strategy to manage the therapy of lung cancer in clinic." (PMID 27046058, 2016). "Therefore, we concluded that TCF-4 expression might positively correlate with MMP-15 levels in lung cancer." (PMID 27046058, 2016). "In contrast, LPP directly regulates MMP15 to degrade N-cadherin, which results in inhibition of EMT in lung cancer." (PMID 37422473, 2023). "Here we found that expression of TCF-4 and MMP-15 was increased in lung cancer cells or tissues versus the normal ones." (PMID 27046058, 2016).
ovarian carcinoma (6 papers, 2014 to 2022). A malignant neoplasm originating from the surface ovarian epithelium. "It has been observed that HLA-G expression in ovarian cell line upregulates matrix metalloproteinase 15 (MMP-15) expression in these cells and a correlation between HLA-G and MMP-15 expression is also seen in ovarian cancer patients." (PMID 33213057, 2020). "Findings also revealed that HLA-G expression in ovarian cancer cells could enhance the tumor cell migration and metastasis in tumor-bearing immunodeficient nude mice through induction of matrix metalloproteinase-15 (MMP-15) expression." (PMID 33329527, 2020). "Upregulation of MMP15 by HLA-G might result in invasiveness or metastasis of ovarian cancer." (PMID 32887509, 2020). "While MMP15 was still significantly overexpressed in ovarian cancer biopsies, CLDN6 did not meet these criteria in a bigger cohort." (PMID 31336942, 2019).
gastric cancer (4 papers, 2014 to 2020). A primary or metastatic malignant neoplasm involving the stomach. "Whereas, the other study established that MMP15 was found highly expressed in gastric cancer leading to poor prognosis in patients with gastric cancer." (PMID 33323547, 2020).
hepatocellular carcinoma (4 papers, 2016 to 2023). A malignant tumor that arises from hepatocytes. "Likewise, several studies have shown the importance of MMP15 in promoting metastasis in hepatocellular carcinoma and cervical cancer models." (PMID 37835389, 2023). "MMP15 contributes to HBXIP-facilitated metastasis of hepatocellular carcinoma cells." (PMID 32887509, 2020). "MMP15 mediates HBXIP-facilitated migration, invasion and metastasis of hepatocellular carcinoma cells." (PMID 32887509, 2020).
non-small cell lung carcinoma (4 papers, 2015 to 2020). A group of at least three distinct histological types of lung cancer, including non-small cell squamous cell carcinoma, adenocarcinoma, and large cell carcinoma. "Highly expressed MMP15 was also observed in non-small cell lung cancer, promoting angiogenesis and tumor progression." (PMID 33323547, 2020). "For example, matrix metalloprotease (MMP) genes such as MMP9, MMP14, and MMP15, which are usually overexpressed in non-small cell lung cancer, also have multiple E2F-binding sites in their promoters, and their expression is regulated by the Rb-E2F pathway." (PMID 26555075, 2015).
prostate carcinoma (4 papers, 2005 to 2020). A carcinoma that arises from epithelial cells of the prostate gland. "MMP15 is reported to be associated with prostate cancer progression, using the expression analysis of human prostatic tissues." (PMID 32887509, 2020). "Among them, the expression of MMP-15 and MMP-26 correlated positively with Gleason score, but the biology and prognostic potential of these two MMPs need to be further investigated in prostate cancer." (PMID 24978435, 2014).
cervical carcinoma (3 papers, 2018 to 2023). A carcinoma arising from either the exocervical squamous epithelium or the endocervical glandular epithelium. "High expression of MMP15 is confirmed in the human cervical cancer, is significantly associated with the shorter overall survival rate (OS) and is correlated with PROK2 expression." (PMID 32887509, 2020). "Overexpression of PROK2 using PROK2 plasmid significantly reverses the function of knockdown PROK2, and further upregulates MMP15 expression, migration and invasion of human cervical cancer cells." (PMID 32887509, 2020). "PROK2 knockdown in cervical cancer cells considerably suppressed the capacity in cellular migration, invasion, and MMP15 expression." (PMID 32887509, 2020). "Cervical cancer patients with high MMP15 expression have a shorter OS than those with low MMP15 expression." (PMID 32887509, 2020). "GEPIA database was also used to further confirm the high mRNA level of MMP15 in human cervical cancer tissues compared with those in the normal cervical tissues." (PMID 32887509, 2020). "In conclusion, we demonstrated that PROK2 regulation of cell migration and invasion of human cervical cancer cells by targeting MMP15." (PMID 32887509, 2020). "We measured the effect of PROK2 on protein and mRNA expressions of MMP15 in human cervical cancer HeLa cells by using RT-qPCR and immunoblot assays." (PMID 32887509, 2020). "In addition, we also revealed that cervical cancer patients with high expression of MMP15 had a shorter overall survival (OS) (HR = 1.8, 95% CI 1.06–3.05, p = 0.027) than those with low MMP15 expression." (PMID 32887509, 2020). "Change of MMP15 expression by PROK2 may contribute to cervical cancer metastasis." (PMID 32887509, 2020). "Cervical cancer patients with MMP15 overexpression have a shorter OS; (v) PROK2-expressing vector reverses PROK2 shRNA-inhibited MMP15 expression, migration and invasion of cervical cancer cells." (PMID 32887509, 2020). "Cervical cancer cells transfected with PROK2 shRNA had a significant decrease in the transcription and translation of MMP15." (PMID 32887509, 2020). "The relation between MMP15 and PROK2 expressions have been further investigated in human cervical cancer." (PMID 32887509, 2020).
colorectal cancer (3 papers, 2021 to 2023). A primary or metastatic malignant neoplasm that affects the colon or rectum. "Finally, several matrix metalloproteinases (Mmp14, Mmp15, Mmp19), which are linked to poor prognosis of liver or colorectal cancer patients, are also upregulated by P2-HNF4α and dysregulation of genes involved in drug metabolism could impact treatment of liver cancer." (PMID 38111711, 2023). "According to our findings, MMP-15 is an anti-apoptotic factor and a prognostic predictor for disease-free survival in colorectal cancer." (PMID 34830271, 2021). "MMP1–MMP4, MMP7–MMP14, and MMP24 were significantly upregulated in colorectal cancer samples, while MMP15, MMP17, MMP19, and MMP24–MMP28 were significantly downregulated in colorectal cancer samples." (PMID 34804973, 2021).